RB1 (RB transcriptional corepressor 1)
Diseases named in the same sentence as RB1 in open-access papers (continued):
Sharing a sentence is not in itself a finding about the gene and the disease.
bladder urothelial carcinoma (9 papers, 2001 to 2025).
carcinoma in situ (9 papers, 2016 to 2025). "Loss of one RB1 allele was common across large areas of urothelium in four of the five patients, suggesting clonal expansion, and subsequent loss of the second RB1 allele was common in severe dysplasia, carcinoma in situ, or urothelial cancer." (PMID 40566675, 2025).
chondrosarcoma (9 papers, 1989 to 2026). A malignant cartilaginous matrix-producing mesenchymal neoplasm arising from the bone and soft tissue. "Our results suggest that deletions in cell cycle regulators CDKN2A and RB1 are associated with increased radioresistance in chondrosarcoma explant tissue." (PMID 31160965, 2019). "Previous studies in chondrosarcoma cell lines (CS-7, CS-8, CS-9) showed that restoring P16 expression, and thereby increasing Rb1 phosphorylation, resulted in an increased radiosensitivity, in line with our results." (PMID 31160965, 2019).
chondrosarcoma (continued). "In addition, we identified alterations in CDKN2A/RB1 as predictors of decreased double strand break formation after radiotherapy in chondrosarcoma tissue, and although further research is necessary in a larger group, this suggests that these patients might benefit less from radiation therapy." (PMID 31160965, 2019). "Although we see a clear difference in the amount of foci in tumors with and without deletions in CDKN2A or RB1, this study is based on a small heterogenous group of chondrosarcomas and measurements are taken after 2 or 24 h." (PMID 31160965, 2019).
esophageal cancer (9 papers, 2011 to 2026). A primary or metastatic malignant neoplasm involving the esophagus. "Lastly, esophageal cancer often exhibits intrachromosomal amplification of MYC, ERBB2, EGFR, RB1, GATA4/6, CCND1, RTK and MDM2 as well as ecDNA-associated amplification of MYC and MDM2." (PMID 41415205, 2025). "However, the identified candidate genes within this region, such as RB1, BRCA2, and ING1, seldom show mutations in esophageal cancer, implying that other unknown tumor-suppressor genes within this region might participate in the tumorigenesis of this cancer." (PMID 22174605, 2011).
Insulin resistance (9 papers, 2015 to 2023). Increased resistance towards insulin, that is, diminished effectiveness of insulin in reducing blood glucose levels. "Lastly, the regulatory mechanisms underlying the effects of BBR+Rb1 on cell proliferation, inflammation, adipogenesis, and insulin resistance in the TNF-α-treated adipocytes were studied by introducing RANKL, which is an agonist of the NF-κB pathway." (PMID 34699329, 2021). "In summary, Rb1 supplementation improved HFD induced insulin resistance in mice, and was associated with profound changes in microbial composition and amino acid metabolism." (PMID 34899310, 2021). "Overall, we find Rb1 treatment by oral administration improves hyperlipidemia, hyperinsulinemia, and insulin resistance in HFD-fed mice." (PMID 35516426, 2022). "Taken together, Rb1 treatment has consistent results in mice and rats and thus strongly suggests that Rb1 treatment improves the lipid metabolism and insulin resistance in HFD-fed rodents." (PMID 35516426, 2022). "The results showed that Rb1 supplementation for mice prevented insulin resistance induced by HFD feeding." (PMID 34899310, 2021). "Afterward, we investigated the effects of BBR combined with Rb1 on cell proliferation, inflammation state, adipogenesis, and insulin resistance in TNF-α-treated adipocytes." (PMID 34699329, 2021). "It is reported that Rb1 can improve insulin resistance, induce hemangiectasis, and suppress lipid peroxidation." (PMID 34699329, 2021). "Therefore, Rb1 might affect macrophage activation through PPARγ, which might alleviate obese insulin resistance in T2D early stage." (PMID 37049846, 2023). "In addition, a few reports show that Rb1 could alleviate insulin resistance in mechanisms." (PMID 37049846, 2023). "Rb1 supplementation decreased levels of BCAAs, and improved HFD induced insulin resistance." (PMID 35923208, 2022). "In addition, it has been found that Rb1 can improve metabolic disorders in high-fat diet-induced obese mice related to gut microbiota regulation, and oral administration of Rb1 significantly reduces serum LDL-c, TG, insulin, and insulin resistance index (HOMA-IR) in high-fat diet (HFD) mice." (PMID 37049846, 2023).
meningioma (9 papers, 2015 to 2024). A generally slow growing tumor attached to the dura mater. "In this context, miR-335–5p appears to influence meningioma cell proliferation by directly affecting the Rb1 pathway." (PMID 38577017, 2024). "Cell proliferation is increased in U87 cells via Wnt/PCP signaling by miR-335 decreasing DAAM expression and miR-335 targets RB1 in meningioma cells resulting in increased cell growth and inhibited cell cycle arrest at the GO/G1 transition." (PMID 26204513, 2015). "Thus, the effect of miR-335–5p on the Rb1 pathway represents an important discovery in understanding the molecular mechanisms of meningioma development." (PMID 38577017, 2024). "We hypothesize that RB1 S780 hyperphosphorylation is the result of genetic and/or epigenetic alterations and an early event in aggressive progression in meningiomas." (PMID 33346248, 2020). "RNAseq of primary (mng_50, mng_20, mng_84, mng_46) and established meningioma cell lines (IOMM-Lee, CH157) demonstrated increased CDKN2A expression in mng_46 and mng_84 cell lines and decreased RB1 expression." (PMID 37093270, 2023). "Staining of RB1 S780 is also found in half of the WHO grade 2 and 3 meningiomas displaying aggressive invasion and spread." (PMID 33346248, 2020). "Our results demonstrate hyperphosphorylation of RB1 Ser780 and increased CCND1, CDK4, and CDK6 expression in high-grade meningiomas and after AKAP12 knockdown." (PMID 29391485, 2018). "CDKN2A deleted meningiomas did not harbour SMARCB1, AKT1, PIK3CA, SMO, POLR2A, or RB1 somatic mutations." (PMID 37093270, 2023). "Genomic sequencing was also performed and mutations in NF2, TRAF7, SMO, KLF4, and AKT1 did not predict RB1 S780 staining or progression in grade 1.5 meningiomas." (PMID 33346248, 2020).
pancreatic NEC (9 papers, 2018 to 2025). "In a report on pancreatic NEC given platinum-treatment, RR was significantly higher for RB1 loss and/or KRAS mutation." (PMID 38909137, 2024).
acute lymphoblastic leukemia (8 papers, 2014 to 2022). Leukemia with an acute onset, characterized by the presence of lymphoblasts in the bone marrow and the peripheral blood. "For instance, familial acute lymphoblastic leukemia (ALL) was confirmed in siblings or dizygotic twins, and retinoblastoma was described among family members with confirmed RB1 gene mutation." (PMID 35205416, 2022). "Thus, loss of function of the RB1 gene drives tumorigenesis in many adult and pediatric cancers including OS, retinoblastoma, medulloblastoma, supratentorial primitive neuroectodermal tumor (sPNET), and acute lymphoblastic leukemia (ALL)." (PMID 26380245, 2015). "Initially described in retinoblastoma, in which it modeled the principle of TSG, RB1 is also reported in chronic lymphocytic leukemia and Acute Lymphoblastic Leukemia (ALL)." (PMID 36077669, 2022). "Pediatric B-cell precursor acute lymphoblastic leukemia (BCP-ALL) is associated with a high frequency of copy number alterations (CNAs) in IKZF1, EBF1, PAX5, CDKN2A/B, RB1, BTG1, ETV6, and/or the PAR1 region (henceforth: B-cell development genes)." (PMID 30874617, 2019).
bone tumor (8 papers, 2010 to 2025). "Because the Rb1 and Pten tumor suppressor genes are frequently mutated in bone cancer, we predicted that their combined deletion might provoke a stronger tumor phenotype than individual deletion of either gene." (PMID 26317218, 2015).
brain cancer (8 papers, 2016 to 2022). A primary or metastatic malignant neoplasm affecting the brain. "Understanding how RB1 loss affects epigenetic control in neural stem and progenitor cells during development and in brain cancer is important for identifying new pathways that contribute to carcinogenesis." (PMID 29914980, 2018). "Together with the survival-promoting activity of RBBP4, HDAC1 and RBBP4 might cooperate to drive persistent proliferation and growth of tumor cells in RB1 mutant brain cancer." (PMID 29914980, 2018).
cardiac hypertrophy (8 papers, 2015 to 2025). "Similar to the mechanism of action of Rb1, Rd can significantly improve the systolic dysfunction, fibrosis, myocardial hypertrophy, inflammation and oxidative stress caused by pressure load in mice." (PMID 37547332, 2023). "Ginsenosides Rg1 and Rb1 are effective in protecting cardiac hypertrophy associated with the activity of Ca2+-calcineurin signaling pathways." (PMID 28841143, 2017). "Histological analysis indicated that myocardial hypertrophy, the fibrosis area, and extracellular matrix deposition in the heart in the diabetic group were improved after insulin and Rb1 treatment." (PMID 38961333, 2024). "In vivo, Rb1 reduced angiotensin II induced myocardial hypertrophy, heart inflammation, and systemic inflammation." (PMID 37547332, 2023). "Inhibition of RB1 has been shown to induce cardiac hypertrophy." (PMID 39436707, 2024). "The pharmacological significance of Rb1 on improving myocardial hypertrophy was investigated." (PMID 37547332, 2023). "The effect of Rb1 in preventing myocardial hypertrophy may be through inhibition of inflammatory mechanisms." (PMID 37547332, 2023). "AMPK participates in the cardiovascular protection effect of Rb1 against reperfusion injury/myocardial ischemia, coronary atherosclerotic, heart failure, cardiac hypertrophy, and fibrosis by mediating apoptosis, autophagy, mitochondrial fission, fatty acid β-oxidation, and aging." (PMID 34712140, 2021).